OR2B11 (olfactory receptor family 2 subfamily B member 11)
Description:
Odorant receptor.
Tractability: Small molecule: it belongs to a druggable protein family. Antibody: its Gene Ontology location is reachable by antibodies, with high confidence; UniProt places it where antibodies can reach, with medium confidence; UniProt predicts a signal peptide or a membrane-spanning region.
Gene: Protein-coding gene on chromosome 1 (247,449,118 to 247,458,105, reverse strand). Ensembl gene ENSG00000177535.
Subcellular location: Cell membrane
Pathways (Reactome):
Sensory Perception: Expression and translocation of olfactory receptors; Olfactory Signaling Pathway
Gene Ontology:
Molecular function: olfactory receptor activity; G protein-coupled receptor activity
Biological process: detection of chemical stimulus involved in sensory perception of smell; G protein-coupled receptor signaling pathway
Cellular component: plasma membrane; membrane
Genetic constraint (gnomAD): Missense variants: 394 observed, 387.34 expected, observed/expected ratio (o/e) 1.02, 90% interval 0.94 to 1.11. Synonymous variants: 191 observed, 171.47 expected, observed/expected ratio (o/e) 1.11, 90% interval 0.99 to 1.26.
Homologues: Orthologues: chimpanzee OR2B11 (98% identical), macaque OR2B11 (95% identical), pig OR2B11 (90% identical), rabbit OR2B11 (88% identical), mouse Or2b11 (87% identical), dog OR2B11 (85% identical), rat Or2b11 (84% identical), guinea pig OR2B11 (79% identical). Paralogues in human: OR2B3 (57% identical), OR2B6 (57% identical), OR2G3 (56% identical), OR2B2 (56% identical), OR2H2 (55% identical), OR2H1 (55% identical), OR2G6 (54% identical), OR2J2 (53% identical), OR2W3 (53% identical), OR2C1 (53% identical), OR2C3 (53% identical), OR2G2 (53% identical), and 80 more.
Diseases named in the same sentence as OR2B11 in open-access papers:
OR2B11 is named in the same sentence as 5 diseases in open-access papers, as found by Europe PMC text mining. Sharing a sentence is not in itself a finding about the gene and the disease. The quoted sentences say what the papers report.
tumor (1 paper, 2024). "The specific expression of OR4N2 in neoplastic cells suggests a possible role in tumor cell survival or proliferation, whereas the up-regulation of OR2B11 in TAMs points to a role in shaping the TME to support tumor growth." (PMID 39769144, 2024). "Collectively, these results suggest that OR2B11 may serve as a potential therapeutic target for GBM by promoting mesenchymal transition and immunosuppressive TME through TAM regulation, potentially driving aggressive tumor behavior." (PMID 39769144, 2024).
OR2B11 also shares sentences with these, for which no sentence is quoted: asthma (1 paper); cancer (1); neurodegenerative disease (1); Parkinson disease (1).